IL7 (interleukin 7)
Diseases named in the same sentence as IL7 in open-access papers (continued):
Sharing a sentence is not in itself a finding about the gene and the disease.
Obesity (22 papers, 2010 to 2025). Accumulation of substantial excess body fat. "Altogether, IL-7 protected from obesity and metabolic alterations induced by MSG associated with a neuroprotective effect in the ARC." (PMID 20376352, 2010). "Nutritional supplementation with ME7, ME10- and/or exercise training was able to facilitate a lowered circulating concentration of cytokines which have been associated with obesity (including IL-6, IL-7, and IL-8), which was mirrored by lowered mRNA expression of these markers in WAT." (PMID 34835983, 2021). "Moreover, IL-7 treatment also greatly improved obesity-associated disorders with a complete restoration of insulin sensitivity, and a partial improvement of the glucose tolerance in adulthood." (PMID 20376352, 2010). "Obesity is also associated with the production of several adipocytokines hypothesized to promote oncogenesis, including leptin, tumor necrosis factor-alpha (TNFα), interleukin-6 (IL-6), IL-7, and IL-8." (PMID 33105727, 2020). "This study is, to our knowledge, the first to explore the impact of acute moderate aerobic exercise on IL‐7 in individuals with obesity." (PMID 39722170, 2024). "Elevated plasma levels of C-reactive protein (CRP) and pro-inflammatory cytokines such as IL-6, TNF-α, MCP-1, IL-8, and IL-7 confirmed the existence of an inflammatory state in individuals with obesity." (PMID 35896710, 2022). "Twenty-four-hour average plasma IL-7 levels were lower in individuals with obesity compared to those with AN restrictive type, constitutional thinness or normal weight controls." (PMID 35911732, 2022). "For instance IL-15 with its anti-obesity effect, TGF-β and IL-7 with their immunosuppressive properties are decreased with obesity in BM." (PMID 32477271, 2020). "In conclusion, high fat diet-induced obesity suppressed the protein expression of IL-7, IL-8, IL-6, CXCR2, and VEGF in skeletal muscle." (PMID 32295130, 2020). "In obesity, the secretion of multiple cytokines including IL-3, IL-7, IL-8, TNFα and chemokines including monocyte chemotactic protein-1 (MCP-1, also called Chemokine C-C motif ligand 2 (CCL2)), are upregulated." (PMID 33105727, 2020). "Healthy obesity, with low IL-7, is once again in mirror image of constitutional thinness with normal high IL-7." (PMID 27611669, 2016). "A protective role of IL-7 against obesity and insulin resistance has been suggested in IL-7-treated mice after pharmacological destruction of hypothalamus by monosodium glutamate or gold thioglucose (IW, unpublished observation)." (PMID 22768283, 2012). "The results we obtained in the immunodeficient HFD-SCID model bring some further clues on how IL-7 protects towards glucose intolerance in a context of obesity." (PMID 22768283, 2012). "The fact that acute IL-7 injection does not impact on any of these parameters in SD-fed mice supports that a pro-inflammatory and/or energy imbalance, such as the one triggered by obesity, is necessary for IL-7 to fully exert its regulatory effect." (PMID 22768283, 2012). "IL-7 not only protected from obesity development but also reduced food intake by directly targeting the hypothalamus, and more precisely the ARC." (PMID 20376352, 2010). "Since MSG promotes obesity development via a neurotoxic effect on the ARC, we evaluated if the beneficial effects of IL-7 on MSG treatment were associated with changes in this hypothalamic nucleus." (PMID 20376352, 2010). "Acute subcutaneous injection of IL-7 prevented monosodium glutamate-induced obesity, this being correlated with partial protection against cell death in the hypothalamic arcuate nucleus (ARC)." (PMID 20376352, 2010). "We have recently obtained evidence that overexpression of interleukin (IL)-7, a critical cytokine involved in lymphopoiesis, can protect against the development of diet-induced obesity in mice." (PMID 20376352, 2010).
Obesity (continued). "However, IL-7 expression decreases with aging, obesity, and high-fat diet intake, factors that also negatively impact muscle regeneration and immune function." (PMID 41441428, 2025). "Additionally, the IL-7 signaling pathway, which plays a role in cellular immune response, was exclusively overrepresented in the generational obesity group." (PMID 39339686, 2024). "This could potentially be attributed to the exercise intensity, which may not have been sufficient to increase IL‐7 levels, despite previous reports suggesting higher IL‐7 levels in individuals with obesity." (PMID 39722170, 2024). "It is therefore too early to speculate on a possible role of this low IL-7 value in healthy obesity." (PMID 27611669, 2016). "Finally opposite levels of IL-7 between CT and OB is, along with other peptides, another data suggesting that constitutional thinness is the mirror image of healthy obesity." (PMID 27611669, 2016). "Oppositely, a recent study showed that IL-7 might protect rodents from obesity through regulation of adipose tissue via a lymphocyte-independent mechanism." (PMID 27611669, 2016). "Moreover, in the high-fat diet (HFD)-induced obesity model, a single administration of IL-7 to C57BL/6 mice is sufficient to prevent HFD-induced WAT mass increase and glucose intolerance." (PMID 22768283, 2012). "Thus we assessed the consequences of a single subcutaneous injection of recombinant murine IL-7 in the more pathophysiological model of high-fat diet (HFD)-induced obesity." (PMID 22768283, 2012). "We recently extended IL-7 pleiotropic effects to energy balance regulation; indeed we reported that IL-7 directly targets the hypothalamic arcuate nucleus and protects mice from the development of monosodium glutamate-induced obesity." (PMID 22768283, 2012). "At that stage of our work, we hypothesized that IL-7 might impact on WAT mass increase and metabolic dysfunctions associated with the development of obesity, such as insulin and glucose intolerance." (PMID 22768283, 2012). "Severity of obesity resulted to be associated with lower plasma levels of oxytocin (p = 0.053), vitamin D deficiency (p = 0.006) and higher plasma levels of IFN-γ (p = 0.004), IL-6 (p = 0.013), IL-7 (p = 0.013), TNF-alpha (p = 0.036) and chemokine ligand 3 (CCL3) (p = 0.013, R2 = 0.03)." (PMID 33809270, 2021). "The trend towards suppressed expression of Il-7 following only 2 d of HFD demonstrates how susceptible the BM niche, and the cells which rely on it, are to diet, which ultimately could contribute to disease susceptibility in metabolic disorders such as obesity." (PMID 24595332, 2014). "We thus analyzed the consequences of acute IL-7 administration on fat mass accumulation, glucose intolerance and WAT inflammation in the high-fat diet (HFD)-induced obesity model in C57BL/6 mice." (PMID 22768283, 2012). "Based on our findings, it does not seem that IL‐7 can affect appetite suppression in response to exercise in males with obesity." (PMID 39722170, 2024). "The fact that the expression of these genes was unaffected implies that IL-7+ osteoblasts, and not other niche cells and ligands, were impacted by obesity in a targeted, rather than generalized manner." (PMID 24595332, 2014). "Previous studies have shown that IL-7 is produced by the human obese white adipose tissue (WAT) yet its potential role on WAT development and function in obesity remains unknown." (PMID 22768283, 2012). "Other immune molecules, including INF-γ, IL-7, IL-10 and α-MSH/IgG, may have negative associations with obesity-related eating behaviors." (PMID 35911732, 2022). "Notably, in men with obesity and DM2, the genes up-regulated due to bright light include fibroblast growth factor 1 (FGF1), vasorin (VASN), ribonuclease A family member 1 (RNASE1), pappalysin 1 (PAPPA), Interleukin 7 (IL7), and fatty acid binding protein 3 (FABP3)." (PMID 40981208, 2025).
Obesity (continued). "However, despite this central effect, a peripheral role of IL-7 in the protection against MSG-induced obesity and metabolic alterations could not be excluded." (PMID 20376352, 2010). "Indeed, in induced-obesity animal models, IL-7 administration prevented from weight gain, by a mechanism independent of lymphocyte cells in which IL-7 could act as a negative regulatory factor of adipocytes differentiation and a positive regulator of lipolysis." (PMID 27611669, 2016).
glioblastoma (21 papers, 2019 to 2025). The most malignant astrocytic tumor (WHO grade IV). "IL-7 expansion of hPBMCs from both healthy volunteers and patients with glioblastoma upregulates lymphocyte VLA-4 expression." (PMID 40244705, 2025). "In our study, RNA sequencing of CD8+ T cells from patients with glioblastoma similarly identified that transcription of VLA-4 was greatest when expanding with IL-7." (PMID 40244705, 2025). "We observed similar results for IL-2– and IL-7–expanded glioblastoma patient CD8+ T cells in terms of CD107aHi degranulation, IFN-γ, and tumor-necrosis factor-alpha (TNF-α) production." (PMID 40244705, 2025). "IL-7–expanded CD8+ T cells demonstrate increased accumulation within orthotopic glioblastoma models despite endogenous T cell sequestration in bone marrow." (PMID 40244705, 2025). "To evaluate IL-7’s effect on migratory integrin expression, we performed bulk RNA sequencing using the same glioblastoma hPBMC samples." (PMID 40244705, 2025). "The goal of this study is to apply the IL7/CCL19‐producing technology to make anti-EGFRvIII or HER2 CAR-T more offensive to glioblastoma and pancreatic cancer, so as to improve the therapeutic efficacy." (PMID 39240078, 2024). "The co-expression of IL-7 and IL-7 Flt3L CAR-T cells improves the therapeutic efficacy of heterogeneous glioblastoma in mice." (PMID 38675377, 2024). "This study explored the therapeutic potential and immunologic mechanisms of IL7/CCL19-producing CAR-T therapy in preclinical solid cancer models of glioblastoma and pancreatic cancer." (PMID 39240078, 2024). "Potentially IL7 or IL7 Flt3L CAR T cells can provide new opportunities to combine CAR T cells with other immunotherapies for the treatment of glioblastoma." (PMID 36817432, 2023). "IL7 expressing CAR T cells improved overall survival in mice pre-treated with a non-lymphodepleting dose of irradiation – allowing for retention of host immune cells – thus, the use of IL7 expressing CAR T cells can open opportunities for combinations of other immunotherapies in glioblastoma." (PMID 36817432, 2023). "Examples of Ovs associated with CAR-T cells are given by Ovs expressing IL-15/il-15Rα, potentiating the antitumor effect of EGFR-CAR-NK cells in GBM mouse models, or Ovs expressing IL-7, improving the efficacy of B7H3-CAR-T cells for glioblastoma therapy." (PMID 39199683, 2024). "Here, we describe the clinical results of treatment of recurrent glioblastoma (GBM) with a long‐acting engineered version of recombinant human IL‐7 (rhIL‐7‐hyFc)." (PMID 36583472, 2023). "To better reflect the capacity for clinical translation, we confirmed that IL-7 exposure upregulated VLA-4 expression on hPBMCs from both healthy donors and patients with glioblastoma." (PMID 40244705, 2025). "In patients with recurrent glioblastoma (n=18), treatment with recombinant interleukin-7 restored and maintained total lymphocyte counts without serious toxicity and irrespective of steroid and temozolomide use." (PMID 38481999, 2024). "In summary, this study revealed that the IL7/CCL19 production technology confers potent antitumor efficacy on CAR-T targeting EGFRvIII or HER2 and can be applicable to CAR-T against intractable solid cancers such as glioblastoma and pancreatic cancer." (PMID 39240078, 2024).
colorectal cancer (20 papers, 2013 to 2026). A primary or metastatic malignant neoplasm that affects the colon or rectum. "In conclusion, 12-week aerobic exercise was associated with increased circulating IL-7 concentrations in colorectal cancer survivors." (PMID 40642656, 2025). "The IL-7 has been less studied in colorectal cancer (CRC) and conditions associated with increased risk of CRC development." (PMID 27866242, 2017). "On the contrary, there are other reports showing that IL-7 is increased in colorectal cancer and it can be used as a diagnostic or prognostic factor in this cancer." (PMID 24551818, 2014). "The potential diagnostic use of circulating GM-CSF and IL-7 and further clinical applications in Iranian patients with colorectal cancer were explored as preliminary data." (PMID 24551818, 2014). "To test this, we treated mice bearing subcutaneous MC38 tumors (a syngeneic model for colorectal cancer) with a single dose of 10 mg/kg Fc-fused IL-7 or Neo-7s and monitored tumor growth." (PMID 41542752, 2026). "Despite these limitations, the approach to investigating both IL-7 and IL-15 provides valuable insights into the effects of exercise on immune-related exerkines in colorectal cancer survivors." (PMID 40642656, 2025). "To clarify the mechanistic relevance of IL-7 and IL-15 in colorectal cancer, we conducted a secondary analysis of the Exercise and Colorectal Cancer Treatment (EXACT) trial." (PMID 40642656, 2025). "Co-culturing of anti-carcinoembryonic antigen (CEA)-specific CAR T cells and CEA-positive LS174T colorectal cancer cells in the presence of IL-7/IL-12-engineered MSCs resulted in enhanced CAR T-cell-driven anti-tumor immune response." (PMID 40643499, 2025). "Intestinal symbionts with preventive or inhibitory effects on colorectal cancer, Bifidobacterium and Lactobacillus reuteri, have been disclosed to have significant regulatory effects on host IL7 expression." (PMID 38289597, 2024). "A clinical trial found that combining IL-7 with chemotherapy significantly improved the survival rate of patients with advanced colorectal cancer." (PMID 38675377, 2024). "Studies have shown that IL-7 can increase the number of tumour-infiltrating lymphocytes in colorectal cancer patients and improve the activity of these cells." (PMID 38675377, 2024). "Recombinant IL-7/IL-12 MSCs are reported to enhance the ability of CAR-T cells to attack colorectal cancer." (PMID 36439438, 2022). "The increase in IL-7 in colorectal cancer (CRC) is related to metastatic disease and tumor location." (PMID 33167940, 2020). "Colorectal cancers, in turn, had significantly higher concentration of IL-7 than other cancers, both when tumor and normal tissue were compared." (PMID 31185636, 2019). "We showed that IL-7 was overexpressed, to different degrees, by esophageal, gastric, and colorectal cancers." (PMID 31185636, 2019). "Despite the central role of IL-7 in innate and adaptive immunity, literature on this cytokine in the context of colorectal cancer is scarce." (PMID 29904108, 2018). "GM-CSF and IL-7 are reported to increase in different cancers and we aimed to investigate the pre-treatment serum levels of GM-CSF and IL-7 in Iranian patients with colorectal cancer." (PMID 24551818, 2014). "There are few reports that have examined GM-CSF in the pathogenesis of colorectal cancer, and the studies on the level of IL-7 in these patients are scarcer." (PMID 24551818, 2014). "Conversely, IL-7 is reported to be elevated in sera of patients with colorectal cancer at stages III and IV." (PMID 24551818, 2014). "There is limited information on the level of IL-7 in colorectal cancer and the results of the available studies are contradictory." (PMID 24551818, 2014). "This study investigated whether a 12-week structured exercise training intervention increases IL-7 and IL-15 in colorectal cancer survivors." (PMID 40642656, 2025).
colorectal cancer (continued). "We hypothesized that 12 weeks of moderate-intensity aerobic exercise compared with a control condition would restore circulating IL-7 and IL-15 in colorectal cancer survivors in a pattern compatible with an improved cancer prognosis." (PMID 40642656, 2025). "Aerobic exercise may improve immune function in colorectal cancer survivors by restoring IL-7 after chemotherapy and improving IL-15 by altering body composition." (PMID 40642656, 2025). "IL-7 has also shown potential in the treatment of colorectal cancer." (PMID 38675377, 2024). "We also suggest that the role of IL-7 in colorectal cancer needs more investigation and may provide a new target in the immunotherapy of colorectal cancer." (PMID 24551818, 2014). "Supporting these findings, Hombach and colleagues recently evaluated the use of genetically engineered IL-7- and IL-12-overexpressing MSCs to augment the efficacy of CAR T cells in colorectal cancer." (PMID 40643499, 2025). "We here report on the use of bone marrow derived MSCs engineered with IL7 and IL12 to sustain a CAR T cell attack against colorectal cancer." (PMID 32260097, 2020). "The interleukin-7 protein is overexpressed in esophageal, gastric, and colorectal cancers, but only CRC and EC patients had significantly elevated IL-7 at the systemic level as compared to healthy controls." (PMID 31185636, 2019). "The 12-week exercise intervention increased circulating IL-7 concentrations in colorectal cancer survivors, irrespective of chemotherapy history." (PMID 40642656, 2025). "Reprogrammed interleukin-7 (IL-7)-IL-12-MSCs are reported to promote the activation of CAR-T immune cells and the release of IFN-γ and tumor necrosis factor-α (TNF-α), which markedly enhanced colorectal cancer cell death." (PMID 36439438, 2022). "C. albicans mediates the up-regulation of macrophage glycolytic pathway, and up-regulates the expression and secretion of IL-7, and then induces type 3 intrinsic lymphocytes (ILC3) to express high levels of IL-22 through AhR and STAT3 pathways, which aggravates the progression of colorectal cancer." (PMID 37333850, 2023).
acute respiratory distress syndrome (19 papers, 2020 to 2025). Progressive and life-threatening pulmonary distress in the absence of an underlying pulmonary condition, usually following major trauma or surgery. "Increased proinflammatory cytokines such as IL-1, IL-2, IL-6, IL-7, IL-10, are frequently observed in many COVID-19 patients, which is closely related to the acute respiratory distress syndrome (ARDS), multiorgan failure and other severe symptoms." (PMID 37228604, 2023). "Massive systemic release of pro-inflammatory mediators such as interleukin (IL)-1β, IL-2, IL-6, IL-7, IL-10, tumor necrosis factor-α (TNFα), granulocyte colony-stimulating factor (G-CSF), etc., also known as cytokine storm, contributes to the acute respiratory distress syndrome (ARDS)." (PMID 35888733, 2022). "Coronavirus disease 2019 (COVID-19)-induced acute respiratory distress syndrome (ARDS) is characterized by hyperinflammation and elevated pro-fibrotic cytokines such as IL-6, IL-7, GM-CSF, MCP, and macrophage inflammatory protein-1α (MIP1α)." (PMID 40343260, 2025). "The overexpression of cytokines such as IL-2, IL-6, IL-7, GSCF, IP10, MCP1, MIP1A, and TNFα is followed by edema, which impairs oxygen exchange, and may lead to acute respiratory distress syndrome (ARDS) causing potential acute cardiac injury, secondary infection, and death." (PMID 32574317, 2020). "Extended sustained low-efficiency dialysis via hemodiafiltration significantly decreased the post-admission levels of IL-17, IL-7, and MCP-1 compared to the dialysis via hemodialysis among patients with acute kidney injury or acute respiratory distress syndrome following leptospirosis." (PMID 32264832, 2020). "This cytokine storm is characterized by elevated plasma concentrations of IL-2, IL-7, IL-10, GCSF, IP-10, MCP-1, MIP-1A and TNF-α, and contributes to the development of acute respiratory distress syndrome (ARDS)." (PMID 34208037, 2021).